SIGLEC5 (sialic acid binding Ig like lectin 5)
Description:
Putative adhesion molecule that mediates sialic-acid dependent binding to cells. Binds equally to alpha-2,3-linked and alpha-2,6-linked sialic acid. The sialic acid recognition site may be masked by cis interactions with sialic acids on the same cell surface.
Synonyms: Siglec-5; OB-BP2; CD170; formerly CD33L2
Gene: Long non-coding RNA gene on chromosome 19 (51,630,101 to 51,645,545, reverse strand). Ensembl gene ENSG00000105501.
Subcellular location: Membrane
Genetic constraint (gnomAD): Loss-of-function variants: 30 observed, 35.16 expected, observed/expected ratio (o/e) 0.85, 90% interval 0.64 to 1.16. The upper end of that interval is the gene's LOEUF score, 1.16, which puts it in group 5 of 6, group 1 being the genes least tolerant of losing a copy. Missense variants: 459 observed, 501.29 expected, observed/expected ratio (o/e) 0.92, 90% interval 0.85 to 0.99. Synonymous variants: 192 observed, 202.8 expected, observed/expected ratio (o/e) 0.95, 90% interval 0.84 to 1.07.
Diseases named in the same sentence as SIGLEC5 in open-access papers:
SIGLEC5 is named in the same sentence as 24 diseases in open-access papers, as found by Europe PMC text mining. Sharing a sentence is not in itself a finding about the gene and the disease. The quoted sentences say what the papers report.
periodontitis (13 papers, 2019 to 2025). An acute or chronic inflammatory process that affects the tissues that surround and support the teeth. "MAFB is suggested to be associated with the activation of SIGLEC5 expression and contribute to early-onset periodontitis." (PMID 39240858, 2024). "These experiments indicated that MAFB regulation is linked with activation of SIGLEC5 expression and with increased risk for early-onset periodontitis." (PMID 34852650, 2022). "Periodontitis risk attributed to the immune receptor gene SIGLEC5 is shown to act via impaired MAFB binding." (PMID 35860693, 2022). "Two large GWASs independently found genetic variants at SIGLEC5 to be associated with different forms of periodontitis, indicating broad relevance of this locus for the disease etiology." (PMID 34852650, 2022). "Recently, a genome-wide association study and 2 genome-wide association study meta-analyses found 2 associated regions (haplotype blocks) at the inhibitory immune receptor gene SIGLEC5 to increase the risk for periodontitis." (PMID 34852650, 2022). "We, therefore, used four SNPs, in LOC107984137, MTND1P5, DEFA1A3, and SIGLEC5 loci, previously associated with periodontitis in GWAS, as instruments for making causal inferences about the role of periodontitis in human BP regulation." (PMID 31504461, 2019). "Increasing transcription of SIGLEC5 was predicted to associate with increasing odds of periodontitis/loose teeth (P = 8.7 × 10−07)." (PMID 31235808, 2019). "Additionally, a study that integrated expression quantitative trait locus (eQTL) data with GWAS associations implied SIGLEC5 as periodontitis risk gene." (PMID 34852650, 2022). "Interestingly, EZH1 and MRPS23 were newly identified, whereas previous studies have verified SIGLEC14 and SIGLEC5 as genetic risk factors for periodontitis." (PMID 36611863, 2022). "Currently, the available dataset for GWAS related to early onset (grade C) periodontitis identified potentially predisposing variants in the genes of DEFA1A3, FCER1G and SIGLEC5 at the level of genome‐wide significance." (PMID 40197750, 2025). "These are located at the genes SIGLEC5, DEFA1A3 and FCER1G, and those are associated with periodontitis at a genome‐wide significance level." (PMID 40197750, 2025). "Genome-wide association studies showed the relationship of NIN, ABHD12B, WHAMM, AP3B2, and SIGLEC5 with chronic periodontitis." (PMID 36360171, 2022). "Further investigation of SIGLEC5 in periodontitis pathologies and intervention targeting the biological pathway underpinned by SIGLEC5 may contributes to both aetiology understanding and disease treatment." (PMID 39240858, 2024). "Because the underlying molecular mechanisms of periodontitis are still largely unclear, the effects of the NIN and SIGLEC5 genes on periodontitis have not been clarified, although significant associations with periodontitis were identified in the European population." (PMID 30765789, 2019). "Finally, we identified two previously reported genes (SIGLEC5, SIGLEC14) and two novel genes (EZH1, MRPS23), proving that TWAS is a supplemental strategy for studying periodontitis’ etiology." (PMID 36611863, 2022). "Since the underlying molecular mechanisms of periodontitis are still unclear, the effects of the NIN, ABHD12B, WHAMM, AP3B2, and SIGLEC5 genes on periodontitis have not been elucidated." (PMID 36360171, 2022).
colorectal cancer (5 papers, 2021 to 2023). A primary or metastatic malignant neoplasm that affects the colon or rectum. "In a cohort of 114 patients with colorectal cancer, our data confirmed the relevance of soluble SIGLEC5 levels as a prognosis marker and exitus predictor." (PMID 34359797, 2021). "Soluble SIGLEC5 has also been identified as a prognostic marker in colorectal cancer patients." (PMID 37465100, 2023). "Furthermore, SIGLEC-5 is upregulated in several types of tumors, including glioma and colorectal cancer and has been proposed as a prognosis marker to predict patient outcome." (PMID 37854605, 2023). "Additionally, the role of SIGLEC5 as an immune evasion molecule in colorectal cancer was evaluated." (PMID 35884505, 2022). "Finally, SIGLEC5 is suggested as a prognostic marker for colorectal cancer but we found no previously published association with ovarian cancer." (PMID 35406529, 2022).
glioma (3 papers, 2021 to 2023). A benign or malignant brain and spinal cord tumor that arises from glial cells (astrocytes, oligodendrocytes, ependymal cells). "In THP-1 cells grown in the presence of U87MG glioma, the exposure to Dex or TMZ caused decreased SIGLEC5 transcripts levels, but increased expression of SIGLEC14." (PMID 33670244, 2021). "In a recent work, the authors characterized the expression of Siglec5, 7, 9 on MDSC both from peripheral blood and glioma infiltrating cells and found the respective ligands both on GB cell lines and patient-derived glioma tissue samples." (PMID 35682991, 2022).
Sepsis (3 papers, 2021 to 2025). Sepsis is defined as life-threatening organ dysfunction caused by a dysregulated host response to infection. "The structure of SIGLEC5 exhibits strong similarities with that from well-known IC candidates, and it has recently been described as a patent IC candidate in sepsis." (PMID 35625783, 2022). "The SIGLEC5 structure exhibits strong similarities with that from well-known IC candidates, and it has recently been described as a patent IC candidate in sepsis." (PMID 34359797, 2021).
autoimmune disease (2 papers, 2022 to 2025). A disorder resulting from loss of function or tissue destruction of an organ or multiple organs, arising from humoral or cellular immune responses of the individual to their own tissue constituents. "For example, Asian-specific haQTLs provided novel candidate variants in gene loci associated with leprosy (SIGLEC5, TNFSF15) and autoimmune disease (CARD9, IRF5, IL27, FOS) (nd 48)." (PMID 35102304, 2022).
depression (1 paper, 2024). "As a result, we discovered 43 key genes associated with pain–depression comorbidity, along with the identification of RNF24, MGAM, FOS, TKT, and SIGLEC5 as hub genes." (PMID 39125922, 2024).
diabetes (1 paper, 2024). "Finally, the Mendelian randomization phenome-wide association study corroborated MANSC4 as a reliable target capable of mitigating the risk of various forms of diabetes, and it revealed the absence of adverse effects linked to CTRB1, SIGLEC5 and MST1." (PMID 38931433, 2024).
hearing loss (1 paper, 2025). "The discovery that methylation at the promoter regions of DNMT3A, UQCR11, POLQ, and SIGLEC5 has a protective effect against hearing loss suggests a multifaceted mechanism by which epigenetic regulation preserves auditory function." (PMID 40428348, 2025).
hypospadias (1 paper, 2020). Hypospadias is the displacement of the urethral meatus on the ventrum of the penis. "This region on chromosome 19 is characterized by clusters of sialic acid-binding Ig-like lectin (SIGLEC) and kallikrein (KLK) genes, among which we identified likely causal relationships with hypospadias (CD33/SIGLEC3, SIGLEC5, SIGLEC7, KLK5, KLK7, KLK10, KLK13, and KLK14)." (PMID 32728162, 2020).
neuroendocrine neoplasm (1 paper, 2025). Endocrine tumors, also referred to as neuroendocrine tumors (NETs), are defined by a common phenotype which is characterized by the expression of general markers (neuron specific enolase, chromogranin, synaptophysin) and hormone secretion products. "Therefore, SIGLEC5 might not only have a potential prognostic value in neuroendocrine neoplasms, but it could also be implicated in the mechanisms leading to malignant transformation and the resulting poorer clinical outcomes in these tumors." (PMID 40038821, 2025).
tumor (8 papers, 2020 to 2025). "The study also indicated the presence of tumor macrophages (CD68+CD163+CSF1R+SIGLEC5+) associated with immunotherapy resistance." (PMID 40404633, 2025). "KLRC1 and SIGLEC5 mediate immune activation and suppression, respectively, and are involved in tumor immune surveillance." (PMID 41438620, 2025). "In agreement, previous evidence suggested that blocking SIGLEC-5 could serve as a new immune checkpoint blockade strategy to enhance anti-tumor T cell functions." (PMID 37854605, 2023). "In addition, plasma levels of SIGLEC5 correlated with disease stage, tumor dedifferentiation and lymph node infiltration, all which point to its efficacy as a biomarker of CRC evolution." (PMID 34359797, 2021). "Among this receptor family, SIGLEC5 and its soluble form, soluble SIGLEC5 (sSIGLEC5), have been shown to bind the highly sialylated P-selectin glycoprotein ligand-1 (PSGL-1) molecule present on T lymphocytes, promoting tumour progression." (PMID 35625783, 2022).
bacterial infection (1 paper, 2014). "For example, little is known about the role of SIGLEC5, a member of the Siglec family of sialic acid-binding lectins in host response to bacterial infection." (PMID 24912583, 2014).
infection (1 paper, 2019). The state of being infected such as from the introduction of a foreign agent such as serum, vaccine, antigenic substance or organism. "Binding to the inhibitory receptors Siglec‐3, Siglec‐5, Siglec‐9, and Siglec‐11 suppresses the pro‐inflammatory response, which could contribute to decreased clearance of infection and contribute to the relative paucity of symptoms." (PMID 30697344, 2019). "In fact, Siglec‐14 has been shown to counteract the exploitation of Siglec‐5 by GBS, and Siglec‐16 reduces survival of E. coli K1 during infection." (PMID 30697344, 2019).
SIGLEC5 also shares sentences with these, for which no sentence is quoted: cancer (2 papers); chronic periodontitis (2); COVID-19 (1); dental caries (1); ischemia (1); leprosy (1); melanoma (1); meningitis (1); ovarian carcinoma (1); Salmonella Infections (1); septic shock (1).